PRL (prolactin)
Diseases named in the same sentence as PRL in open-access papers (continued):
Sharing a sentence is not in itself a finding about the gene and the disease.
breast cancer (continued). "High circulating PRL is a risk factor for metastatic ERα+ breast cancer, and its cognate receptor (PRLR) is expressed in most breast cancers, especially those expressing ERα." (PMID 25607819, 2015). "Parity, a well-established protective factor for breast cancer, has been associated with a long-term post-pregnancy reduction in levels of circulating prolactin." (PMID 25887963, 2015). "Our study is the second largest prospective study on the association between prolactin and breast cancer risk, to provide risk estimates for in situ breast cancer." (PMID 25887963, 2015). "High PRL levels are directly linked with breast cancer risk and with worse prognosis in breast cancer patients." (PMID 26733941, 2015). "Post-menopausal women with elevated plasma prolactin levels have a significantly higher risk of breast cancer." (PMID 25713759, 2015). "It is peculiar that modulation of ECM by PRL seems to be specifically associated to progression of ER+ breast cancers." (PMID 26733941, 2015). "Increased levels of prolactin and low dehydroepiandrosterone in patients with SSc and breast cancer lend further support to this association." (PMID 24524733, 2014). "In fact, evidence derived from the Nurses Health Study did provide evidence for an association between elevated prolactin levels and breast cancers expressing the estrogen and progesterone receptor." (PMID 24762632, 2014). "Prlh modulates secretion of prolactin, a hormone that has been shown to be a risk factor for human breast cancer." (PMID 23967281, 2013). "In breast cancer, prolactin has been implicated as a tumor promoter based on experimental studies in rodents and the association between elevated circulating prolactin levels and increased risk of developing breast cancer." (PMID 24004716, 2013). "The roles of progestins, prolactin and insulin are less established but one study showed that risk of ductal breast cancer increases ∼4 fold after use of progesterone." (PMID 24170988, 2013). "PRL positively interacted with E2 to further elevate several transcripts encoding growth and progression factors for breast cancer, including AREG, EREG, PTHrP and WT1." (PMID 23758962, 2013). "Prolactin increases the risk of breast cancer and can promote cell proliferation and survival, increase cell motility, and support tumor vascularization." (PMID 23853760, 2013). "Human growth hormone (GH) resembles prolactin in size and overall structure and is also implicated in breast cancer growth and development." (PMID 24004716, 2013). "PRL-modulated transcripts reported in this study are expected to facilitate deciphering of the mechanisms underlying the pleotropic effects of PRL on breast cancer." (PMID 23758962, 2013). "Epidemiological studies performed during the 80s and 90s were unable to reach unified conclusions from correlations between circulating PRL levels and risk for breast cancer." (PMID 24148306, 2013). "Now, there is evidence that high circulating PRL levels are considered a risk factor in breast cancer and in other reproductive cancers such as endometrial, ovarian and prostate." (PMID 24148306, 2013). "PRL promotes mammary tumor formation in rodents and elevated serum prolactin is associated with increased risk of estrogen-receptor positive breast cancer in women." (PMID 23758962, 2013). "This is particularly relevant because women with elevated serum prolactin levels have an increased risk of breast cancer." (PMID 23369183, 2013). "Increased Prlh leading to higher prolactin levels is associated with increased risk for breast cancer, increased metastasis, disease progression, lower response to tamoxifen and worse clinical prognosis." (PMID 23967281, 2013). "In a case-control study within the prospective Nurses' Health Study, plasma level of prolactin was positively associated with the risk of breast cancer." (PMID 23095343, 2012).
breast cancer (continued). "Prolactin has previously been found to be a blood-borne risk marker for breast cancer in postmenopausal women, particularly for estrogen receptor positive (ER+) and progesterone receptor positive (PR+) cancers." (PMID 23202969, 2012). "There is considerable animal and in vitro laboratory evidence to provide a biologic basis for an association between elevated prolactin levels and breast cancer development in humans." (PMID 23227451, 2012). "In this population-based case-control study, we evaluated the association between SSRI use and breast cancer risk as a function of their relative degree of inhibition of serotonin reuptake as a proxy for their impact on prolactin levels." (PMID 23227451, 2012). "A DriverNet prediction not identified by the Frequency approach included JAK1 (p = 0, ranked 13th, mutated in one case), which plays a key role in prolactin signaling, which is implicated in breast cancer." (PMID 23383675, 2012). "We used the FDR method to evaluate the robustness of SNP associations with serum prolactin levels and breast cancer risk." (PMID 21470416, 2011). "Large prospective studies have reported a positive association between prolactin levels and breast cancer risk." (PMID 21470416, 2011). "Estrogens and prolactin likely influence the risk of breast cancer by inducing cell proliferation and tumor growth through the ER and prolactin receptor, respectively." (PMID 22017816, 2011). "In another study, Vaclavicek and colleagues reported that PRL promoter SNPs rs1341239 and rs12210179 were positively associated with familial breast cancer." (PMID 21470416, 2011). "We recently reported that higher prolactin levels were associated with increased breast cancer risk in our population-based case-control study conducted in Poland, and this is consistent with larger cohort studies." (PMID 21470416, 2011). "Studies have suggested that toxic effects of ATR on the nervous system and on the induction of mammary tumors are linked to altered expression of prolactin (PRL)." (PMID 20529762, 2010). "Differentiation of breast cells after a full-term pregnancy, but also a long-term reduction in prolactin levels, have been suggested to explain the protective effect of a childbirth on the risk of breast cancer." (PMID 20492657, 2010). "Using data from a population-based breast cancer case–control study conducted in two cities in Poland (2000–2003), we examined the association of PRL levels with breast cancer risk factors among controls and with tumour characteristics among the cases." (PMID 20736944, 2010). "Previous, smaller case–control and prospective studies (12–71 cases) have generated mixed results regarding the association of PRL levels with breast cancer." (PMID 20736944, 2010). "We also examined associations of serum PRL levels with tumour characteristics among the incident cases of breast cancer." (PMID 20736944, 2010). "Breast cancer risk factors, assessed by interview, were related to serum PRL levels among controls using analysis of variance." (PMID 20736944, 2010). "The associations of PRL levels with other known breast cancer risk factors, including: age at menarche and first birth, benign breast disease, and adult body weight, have mostly been null for both pre- and postmenopausal women, even after adjusting for parity." (PMID 20736944, 2010). "Recent epidemiologic evidence clearly shows that in both pre- and post-menopausal women with serum prolactin levels in the highest quartile have a significant increased risk of developing breast cancer." (PMID 21144038, 2010). "Using a large population-based case–control study conducted in Poland, we explored the association of PRL levels with known breast cancer risk factors in both pre- and postmenopausal women in our control population." (PMID 20736944, 2010). "The association of PRL levels with established breast cancer risk factors was examined among controls." (PMID 20736944, 2010).
breast cancer (continued). "Our analysis of serum PRL levels among population-based controls in the Polish study demonstrated significant relationships with three established breast cancer risk factors: nulliparity, among premenopausal women, and HRT and BMI among postmenopausal women." (PMID 20736944, 2010). "Conclusions regarding the associations of PRL with breast cancer risk factors and tumour characteristics are largely based on a small number of studies and, in some cases, small populations." (PMID 20736944, 2010). "It is plausible that mammographic density is on the causal pathway to breast cancer, as prolactin increases mitosis in the breast." (PMID 19545414, 2009). "There is also a suspected link between elevated plasma prolactin levels and breast cancer, although the causal relationship in this link remains to be established." (PMID 19102734, 2008). "The Janus kinase (JAK)/STAT pathway is important to cell development and differentiation; defects can lead to inhibition of growth restraint, with prolactin implicated in the pathogenesis of human breast cancer." (PMID 21655368, 2008). "Prolactin signalling has also been implicated in mammary and breast cancer, including invasive and non-invasive breast cancer." (PMID 19014541, 2008). "The Nurses Health Study demonstrated that > 1.6-fold difference between upper and lower quartiles of PRL levels was associated with a 34% increase in breast cancer risk." (PMID 18053149, 2007). "There are few prospective epidemiological studies evaluating plasma PRL levels and breast cancer risk." (PMID 18053149, 2007). "The strongest association in PRL between a haplotype and breast cancer risk was with haplotype 3I in block 3 (p = 0.036)." (PMID 18053149, 2007). "Further studies in larger samples are needed to definitively assess the relationship between this polymorphism, plasma PRL levels and breast cancer." (PMID 18053149, 2007). "We found that tagSNP34 (2.1 kb upstream of SNP35 in the promoter region of PRL) had the strongest association with risk of breast cancer (p = 0.049)." (PMID 18053149, 2007). "We evaluated genetic variation in the PRL and PRL receptor (PRLR) genes as predictors of plasma PRL levels and breast cancer risk among African-American, Native Hawaiian, Japanese-American, Latina, and White women in the Multiethnic Cohort Study (MEC)." (PMID 18053149, 2007). "This the largest and most comprehensive study of common genetic variation in PRL pathway genes in relation to breast cancer risk and plasma PRL levels." (PMID 18053149, 2007). "Higher prolactin levels have been associated with an increased risk of postmenopausal breast cancer." (PMID 16523201, 2006). "Studies of the epidemiology have found that high serum prolactin levels were associated with known breast cancer risk factors such as parity status and mammographic breast density." (PMID 15213724, 2004). "Human breast cancer is the leading cause of cancer death in women from Western societies, and a large study of the epidemiology has demonstrated strong associations between human prolactin and risk of breast cancer." (PMID 15213724, 2004). "Human breast cancer is the leading cause of cancer death in women from Western societies, and a large study of the epidemiology demonstrated strong associations between human prolactin and risk of breast cancer." (PMID 15213724, 2004). "The associations of IGF-I and prolactin with risk of breast cancer in the NHS, respectively in pre and postmenopausal women, are thus similar to the associations with mammographic densities according to menopausal status seen in the present study." (PMID 12373602, 2002). "A recent Finnish study further supported these findings, indicating that prolonged exposure to prolactin-increasing antipsychotics may augment breast cancer risk in female schizophrenia patients." (PMID 40465597, 2025).
breast cancer (continued). "Additionally, other breast cancer risk factors, such as nulliparity and high mammographic breast density, have been shown to be correlated with increased levels of serum PRL." (PMID 40160874, 2025). "A possible etiology linking antidepressants to the risk of breast cancer may be through the effect of prolactin." (PMID 38554178, 2025). "Our findings suggest that schizophrenia patients receiving aripiprazole treatment, known for its prolactin-lowering effects, may exhibit a reduced risk of breast cancer development." (PMID 40465597, 2025). "Some epidemiological studies suggested antipsychotic therapy may increase breast cancer risk by elevating prolactin concentration." (PMID 40531900, 2025). "The study has found that traditional antipsychotic drugs may increase the risk of breast cancer, particularly lobular carcinoma, and this is associated with an increase in prolactin levels." (PMID 40465597, 2025). "Breast cancer is recognized as a hormone-dependent malignancy, with increased prolactin concentrations posing a risk factor.The neurophysiological regulation of prolactin has been found to be controlled by dopamine, and it is also believed to potentially promote breast cancer cell proliferation." (PMID 40465597, 2025). "Another study involving 1,400 patients revealed that prolactin was associated with the occurrence of breast cancer, especially in postmenopausal women (relative risk: 1.37, p < 0.05) and in patients with ER + status (relative risk: 1.28, 95% confidence interval: 1.07–1.54, p = 0.003)." (PMID 40160874, 2025). "Two large observational studies reported a significant risk of breast cancer associated with prolactin-related antipsychotics, however whether prolactin-related antipsychotics stimulate breast cancer cell growth remains inconclusive." (PMID 38554178, 2025). "Treatment with selective serotonin reuptake inhibitors (SSRIs) may increase circulating prolactin levels, which could potentially increase the risk of breast cancer by stimulating cellular proliferation, differentiation, and angiogenesis." (PMID 38554178, 2025). "A strong association was found between PRL-secreting PitNETs and a family history of breast cancer." (PMID 40160874, 2025). "This study utilized a retrospective comparative cohort approach, aided by large scale propensity score modeling, to examine the association between use of prolactin increasing antipsychotics and the risk of incident breast cancer in patients diagnosed with schizophrenia." (PMID 38595824, 2024). "Previous studies focussed solely on the associations of higher levels of PRL with health outcomes, and observed an association of higher PRL levels with increased risk of breast cancer in post-menopausal women, including those who used hormone replacement therapy." (PMID 38829475, 2024). "However, we did find that elevated prolactin levels led to an increased risk of breast cancer and ER-positive breast cancer." (PMID 37540479, 2024). "Relative risk of breast cancer for high prolactin-increasing antipsychotic users, compared to non-prolactin-increasing antipsychotic users, we report calibrated hazard ratios (HRs) and their 95% confidence intervals (CIs) and p-value (P), with propensity score (PS) stratification or matching." (PMID 38595824, 2024). "Importantly, the results of this study suggest that exposure to prolactin-increasing antipsychotics for as little as 1 to 4 years is associated with an increased odds of breast cancer." (PMID 38687213, 2024). "In a sensitivity analysis excluding concomitant aripiprazole use time, duration of exposure to prolactin-increasing antipsychotics of 1–<5 years was associated with an aOR for breast cancer of 1.22 (95% CI = 1.05–1.42), and with an aOR of 1.47 (95% CI = 1.26–1.72) for ≥ 5 years exposure." (PMID 38687213, 2024). "Aging Sprague-Dawley rats are susceptible to pituitary tumors, which may enhance mammary tumor formation through elevated circulating prolactin levels." (PMID 38334641, 2024).
breast cancer (continued). "Domperidone and other drugs inducing prolactin release may be contraindicated due to an increased risk of breast cancer development with elevated prolactin." (PMID 37447149, 2023). "This suggests that prolactin may be related to another factor that alters breast cancer risk or that it acts through other biologic pathways, such as NF1-C2, which have yet to be fully elucidated." (PMID 36882838, 2023). "Thus disregulation of the hormone prolactin increases the risk of the development of breast cancer in the life of a female." (PMID 37900385, 2023). "In addition, long-term exposure to antipsychotics that increase prolactin elevate the risk of breast cancer in women and of low-energy fractures." (PMID 37603404, 2023). "Higher circulating prolactin has been associated with increased breast cancer risk." (PMID 36882838, 2023). "Furthermore, epidemiologic studies have linked PRL to mammographic density, a potent independent contributor to increased breast cancer risk." (PMID 35784527, 2022). "More recently, genetically modified mice have permitted interrogation of mechanisms by which PRL may increase risk of breast cancer, apart from ovarian steroids." (PMID 35784527, 2022). "Furthermore, excessive plasma prolactin levels have been associated with an increased risk of breast cancer in both premenopausal and postmenopausal women; is more prominent in estrogen or progestogen receptor cancer type." (PMID 36686654, 2022). "Here we review experimental data implicating multiple mechanisms by which prolactin may increase the risk of breast cancer." (PMID 35784527, 2022). "PRL-increasing and PRL-sparing antipsychotics pose a similar risk of breast cancer." (PMID 36591471, 2022). "Lastly, PRL-increasing and PRL-sparing antipsychotics pose a similar risk of breast cancer." (PMID 36591471, 2022). "In addition, higher plasma prolactin levels are associated with breast cancer risk in a prospective study." (PMID 36425551, 2022). "Further understanding of these interactions apart from the hormonal milieu of pregnancy will provide additional insight into the impact of PRL on increased breast cancer risk in premenopausal women and postmenopausal women treated with estrogen-progesterone MHT." (PMID 35784527, 2022). "Lower circulating levels of PRL along with reduced GH could contribute to the reduced risk of breast cancer in parous animals." (PMID 34206988, 2021). "In large epidemiological studies it has been well documented that elevated circulating PRL levels are correlated with increased breast cancer risk and metastasis in premenopausal women and this risk is greater for ER+ breast cancer and lymph node-positive tumors." (PMID 34572912, 2021). "Human prolactin (hPRL) is a risk factor for primary and metastatic ER+ breast cancer." (PMID 34524841, 2021). "Our results showed that there was a persistent decrease in the tissue and circulating levels of GH and PRL in parous animals, which could play a major role in reducing the risk of breast cancer." (PMID 34206988, 2021). "Although less clearly defined, a loss of responsiveness of breast cancer tissues to the pro-differentiation activities of prolactin might be linked to its pathogenic role in certain breast cancer subtypes and/or disease stages." (PMID 33335078, 2020). "Evidence exists suggesting a link between high prolactin levels and risk of breast cancer development; however, it is unclear whether this is true for BNEN too." (PMID 33584543, 2020). "Beyond its recognized role in the development and differentiation of the normal breast, prolactin causally contributes to the pathogenesis of breast cancer via an autocrine/paracrine loop involving prolactin binding to its membrane-associated prolactin receptor (PRLR)." (PMID 33335078, 2020). "Prolactin is implicated in both breast cancer aetiology and progression." (PMID 32831062, 2020).